ARID2 (AT-rich interaction domain 2)
Diseases named in the same sentence as ARID2 in open-access papers (continued):
Sharing a sentence is not in itself a finding about the gene and the disease.
cancer (continued). "Truncating mutations in SWI-SNF cancer genes, including ARID1A and ARID2, emerged in three of five cancers relapsing after taxane chemotherapy." (PMID 28810143, 2017). "Elucidation of the mechanisms by which the tumor suppressor gene ARID2 plays a role in cancer pathogenesis should pave the way for the development of novel diagnostic and therapeutic strategies against HCC." (PMID 27351279, 2016). "More recently, mutations in ARID2 were identified in NSCLC (7.3%), making this gene one of the most frequently mutated in this type of cancer." (PMID 24622842, 2014). "The AT-rich interactive-containing domain (ARID) gene superfamily consists of seven members (ARID1–5), of which the following have now been implicated in cancer: ARID1A/BAF250a, ARID1B/250b, and ARID2/BAF200." (PMID 24622842, 2014). "Because of the frequent mutations in ARID2 and PBRM1 in some cancers, we explored whether loss of either subunit altered NRF2 signaling." (PMID 38358974, 2024). "Notably, genes encoding PBAF and ncBAF components such as PBRM1, ARID2, BICRAL (GLTSCR1L) and others were found to be more frequently mutated in cancer than in NDD." (PMID 37500730, 2023). "We also detected apparent colocalization of USP2 and ARID2 within cancer cells." (PMID 36567903, 2022). "The SWI/SNF genes, ARID1A, ARID1B, ARID2, SMARCA4, SMARCB1, and PBRM1 were mutated in up to 21.8% of all the cancers, and SWI/SNF mutation carriers had significantly higher TMB values as well as higher TMB-H and MSI-H proportions than their SWI/SNF-non-mutant counterparts in several malignancies." (PMID 36371186, 2022). "When EMT biomarkers were detected in H1299 cells with cotransfection of USP2 shRNAs and ARID2 overexpression vectors, we found that in comparison with cancer cells with USP2 shRNAs transfection, the cotransfection demonstrated notably diminished tendency of mesenchymal phenotype transition." (PMID 36567903, 2022). "Sequencing data from The Cancer Genome Atlas (TCGA) do not reveal major mutation hotspots in ARID2 and alterations are spread all along the gene in all cancers, including HCC." (PMID 32977645, 2020). "Furthermore, our patient had a frameshift mutation of ARID2 which has not been directly involved in HS but has been documented in other cancers." (PMID 40260333, 2025). "Subsequent wound healing assay on the H1299 cells transfected with USP2 shRNAs in combination with or without ARID2 overexpression vectors also suggested that the enhancement of cancer cell migration caused by USP2 shRNAs was also diminished with cotransfection of ARDI2 overexpression." (PMID 36567903, 2022). "Interestingly, TCGA project has shown that ARID2 is not significantly mutated in any individual cancer type studied to date, but is significantly mutated, although at a low frequency, in a pan-cancer analysis." (PMID 25790038, 2015). "Chromatin remodeling factors like ARID2 and ARID1A, essential components of the SWI/SNF complex, are critical in regulating cancer progression and metastasis." (PMID 40872531, 2025). "FTase proteins (FNTA and FNTB) as well as eight of the 116 PFPs are known cancer-relevant proteins as per COSMIC Cancer Gene Census49 or TCGA50 (KRAS, HRAS, NRAS, RHEB, RHOA, DDX3X, ARID2, and SAV1)." (PMID 39995872, 2025).
cancer (continued). "SWI/SNF mutations occur at a high frequency in TC, primarily involving the inactivation of SWI/SNF subunits ARID1A, ARID1B, ARID2, and PMRM1, which were found in several aggressive cancer types, including ATC." (PMID 40203790, 2025). "In conclusion, these genetic findings highlight the importance of understanding the roles of BRAF, ARID2, KMT2C, and GNAQ in different cancer types, shedding light on potential therapeutic targets and predictive markers for cancer treatment strategies." (PMID 38023196, 2023). "The mutational rates and variation types of six SWI/SNF complex genes (ARID1A, ARID1B, ARID2, SMARCA4, SMARCB1, and PBRM1) were analyzed retrospectively by integrating next-generation sequencing data of 4591 cases covering 18 cancer types." (PMID 36371186, 2022). "Genetic alterations in ARID1A (12%), ARID1B (5%), ARID2 (6%) and ARID5B (2.6%) were identified in multiple cancer types." (PMID 35239432, 2022). "For the MSK-IMPACT cohort, we restricted our analysis to 189 ccRCC patients and 2936 patients treated with immunotherapy comprising 11 other cancer types that had a minimum of 50 patients and 5 PBRM1 or ARID2 mutants." (PMID 32820162, 2020). "The combined 208 cases yielded no additional high-frequency mutated genes, however, multiple lower frequency (<2.5% recurrence) cancer-related genes were identified including ATM, ARID2, TGFBR2 and ACVR1B." (PMID 25855536, 2015). "Therefore, targeting ARID2 can enhance the proliferation capacity and antitumor activity of CD8+ T cells in chronic infections and cancer, thereby improving the effectiveness of immunotherapy." (PMID 40342423, 2025). "The therapeutic potential of ERBB3 inhibitors, such as AZD8931, demonstrates that TFE3-RCC cells lacking ARID2 are more sensitive to this treatment, providing promising directions for improving outcomes for patients with this aggressive cancer subtype." (PMID 39727945, 2024). "Tobacco related genes, such as USP9X, ARID2, MLL4, TRPM3 and UNC13C, exactly showed no mutations in buccal mucosal cancer cell lines with no risk-habits of tobacco smoking or chewing." (PMID 36611830, 2022). "Three genes ARID2, LRIF1 and UBE2L6 were not covered by any representative term with only ARID2 being an NCG cancer gene." (PMID 34504716, 2021). "ARID2 is emerging as a tumor metastasis suppressor gene in HCC and cancer in general." (PMID 32977645, 2020). "Although frequent inactivating mutations were detected in an aggressive subtype of HCC, it is still not understood how ARID2 plays tumor suppressor roles in cancer evolution." (PMID 29863171, 2018).
infection (5 papers, 2016 to 2025). The state of being infected such as from the introduction of a foreign agent such as serum, vaccine, antigenic substance or organism. "The results indicated that ARID2 knockdown significantly promoted G1- to S-phase transition in SK-Hep1 cells, especially at 96 hours post-infection." (PMID 27351279, 2016). "Notably, treatment of A549 cells with siRNAs that target BRD9 or GLTSCR1, but not BRD7 or ARID2, led to a reproducible (although not statistically significant) reduction in the ability of IFN‐α2 to fully protect cells from infection with the IFN‐sensitive vesicular stomatitis virus (VSV) (Fig EV1C)." (PMID 34397140, 2021).
kidney diseases (2 papers, 2020 to 2021). "The lncRNA Arid2-IR, located within the intronic region of AT-rich interactive domain 2 gene, was identified by RNAseq analysis of TGFβ-mediated inflammatory pathways in kidney diseases and renal fibrosis." (PMID 33671123, 2021).
neurodevelopmental disorder (2 papers, 2021 to 2025). A behavioral and cognitive disorder with onset during the developmental period that involves impaired or aberrant development of intellectual, motor, or social functions. "The SVM classifier model was trained using the selected ARID2 episignature probes, 75% of controls, and 75% of other neurodevelopmental disorder samples." (PMID 40044822, 2025). "We also assessed peripheral blood DNA methylation profiles in individuals with ARID2-RD compared to episignatures of controls, unresolved cases, and other neurodevelopmental disorders." (PMID 40044822, 2025).
ARID2 also shares sentences with these, for which no sentence is quoted: adenocarcinoma (2 papers); bladder cancer (2); CNS cancers (2); colon (2); colon adenoma (2); glioblastoma (2); type 2 diabetes mellitus (2); Acinic Cell Carcinoma (1); acute lymphoblastic leukaemia (1); adrenal tumor (1); ampullary carcinomas (1); anemia (1); appendiceal adenocarcinomas (1); astrocytoma (1); atrial septal defect (1); autism spectrum disorder (1); Batten disease (1); breast ductal carcinomas (1); carcinoids (1); cervical squamous cell carcinoma (1); Charcot-Marie-Tooth disease type 1A (1); CHOPS syndrome (1); chronic hepatitis (1); Cirrhosis (1); colorectal adenoma (1); congenital heart disease (1); connective tissue disorder (1); deafness (1); diffuse large B-cell lymphoma (1); endometrial carcinoma (1).
A further 50 diseases each share a sentence with ARID2 in 1 paper.